APOE (apolipoprotein E)
Diseases named in the same sentence as APOE in open-access papers (continued):
Sharing a sentence is not in itself a finding about the gene and the disease.
hypertensive nephropathy (1 paper, 2022). Kidney damage that results from chronically elevated blood pressure; complications include glomerular damage resulting in proteinuria and hematuria. "ApoE/NOS3−/− mice had features of hypertensive nephropathy and hypertensive retinopathy." (PMID 36360235, 2022). "We found that ApoE/NOS3−/− mice reproduced normally, had a blood pressure of 133.00 ± 3.85 mmHg, and developed hypertensive fundus retinopathy and hypertensive nephropathy." (PMID 36360235, 2022).
hypoalphalipoproteinemia (1 paper, 2016). A metabolic disorder characterized by deficiency of high density (alpha) lipoprotein in the blood. "The result showed that the APOE genotype was an independent risk factor for hypoalphalipoproteinemia." (PMID 27724906, 2016).
Hypocholesterolemia (1 paper, 2023). An decreased concentration of cholesterol in the blood. "In an investigation that used apoE-knocked out mice fed with a high-fat diet, astaxanthin increased the hepatic levels of LDL receptors, reduced HMG-CoA reductase, and increased Sterol regulatory element-binding protein 2 (SREBP-2), which were associated with hypocholesterolemia effects." (PMID 36678157, 2023).
hypoprothrombinemia (1 paper, 2013). "Therefore, we employed uniformly viable FII heterozygous ApoE−/− mice (characterized by hypoprothrombinemia and diminished FVII and thrombin generation but no spontaneous bleeding risk) in comparative studies with control, prothrombin-sufficient ApoE−/− mice." (PMID 23409043, 2013).
inflammatory skin disease (1 paper, 2022). Inflammatory skin disorders covers a broad category that includes many conditions ranging in severity, from mild itching to grave medical health complications These disorders are common in people of all ages and races. "The relevance of ApoE, DKK1, IL12B, IL9, MANF, and VEGFC in specific inflammatory skin diseases was identified in several previous studies, as discussed further." (PMID 35393522, 2022).
Interstitial cardiac fibrosis (1 paper, 2026). A type of myocardial fibrosis characterized by excessive diffuse collagen accumulation concentrated in interstitial spaces. "Deletion of PACAP expression in ApoE knockout mice markedly accelerated interstitial cardiac fibrosis, under CED‐induced metabolic stress conditions." (PMID 41292235, 2026). "PAC1 deletion in HFD‐fed ApoE knockout mice phenocopied the major pathophysiological consequence of the deletion of PACAP; however, it accelerated interstitial cardiac fibrosis in these mice." (PMID 41292235, 2026).
intracranial aneurysms (1 paper, 2016). "The purpose of this study was to investigate the association between APOE polymorphisms and the risk of intracranial aneurysms in a Chinese population." (PMID 26830841, 2016). "The purpose of this study was to investigate the association between APOE polymorphism and the risk of intracranial aneurysms in a Chinese population." (PMID 26830841, 2016). "The exact molecular mechanism of the association between APOE polymorphism and the risk of intracranial aneurysms remains relatively unclear." (PMID 26830841, 2016). "First of all, although this study suggested that APOE polymorphism was associated with intracranial aneurysms, more biological background data are needed to explain our results." (PMID 26830841, 2016). "Our study suggested that APOE polymorphism might be associated with intracranial aneurysms in Chinese population." (PMID 26830841, 2016). "In conclusion, our study suggested that APOE polymorphism might be associated with intracranial aneurysms in Chinese population." (PMID 26830841, 2016). "Although lot of studies have been conducted to examine the association of genetic polymorphism and intracranial aneurysms, the relationship between the APOE polymorphism and intracranial aneurysms has previously only been studied in Russia and Japan but not in Chinese populations." (PMID 26830841, 2016). "The APOE E4/E4 genotype frequencies (OR = 0.09, 95 % CI = 0.01, 0.74; P = 0.03) in the intracranial aneurysms group were significantly lower than those in the controls group." (PMID 26830841, 2016). "Patients with intracranial aneurysms had a significantly higher frequency of APOE E2/E2 genotype (OR = 9.51, 95 % CI = 1.19, 76.04; P = 0.03) and APOE E2/E3 genotype (OR = 1.87, 95 % CI = 1.03, 3.40; P = 0.04) than healthy controls." (PMID 26830841, 2016). "Patients with intracranial aneurysms had a significantly higher frequency of APOE E2/E2 genotype [odds ratio (OR) =9.51, 95 % confidence interval (CI) = 1.19, 76.04; P = 0.03] and APOE E2/E3 genotype (OR = 1.87, 95 % CI = 1.03, 3.40; P = 0.04) than healthy controls." (PMID 26830841, 2016). "The relationship between the APOE polymorphism and intracranial aneurysms has previously only been studied in Russia and Japan but not in Chinese populations." (PMID 26830841, 2016). "The relationship between the apolipoprotein E (APOE) polymorphism and intracranial aneurysms has previously only been studied in Russia and Japan but not in Chinese populations." (PMID 26830841, 2016).
keratosis (1 paper, 2022). A skin disorder consisting of hypertrophy of the stratum corneum of the skin. "Previous studies have demonstrated abnormal MGs, MG dropout, and abnormal keratosis in apolipoprotein E knockout mice." (PMID 35242100, 2022).
language disorder (1 paper, 2021). A category of disorders characterized by an impairment in the development of an individual's language capabilities, which is in contrast to his/her non-verbal intellect. "The fourth language disorder, lvPPA, did not share any of its four genes (APOE, APP, GRN, MAPT) with the other disorders." (PMID 34539327, 2021).
latent infection (1 paper, 2025). "Finally, ApoE deficiency did not affect the establishment of chronic MHV68 infection under conditions that enrich for latent infection of peritoneal macrophages, suggesting that the proviral effects of ApoE are limited to the lytic viral cycle." (PMID 40439406, 2025). "Importantly, using a route of inoculation that enriches for latent infection of peritoneal macrophages, our study indicates that the proviral role of ApoE is selective for the lytic and not latent MHV68 life cycle." (PMID 40439406, 2025). "Finally, ApoE was not involved in the establishment of MHV68 latent reservoir in the peritoneal cavity under conditions that enrich for latent infection of peritoneal macrophages, indicating that the proviral effects of ApoE in macrophages are likely limited to the lytic viral life cycle." (PMID 40439406, 2025).
Learning disabilities (1 paper, 2023). "Learning disabilities and memory deficits were observed as a consequence of abnormal APOE gene expression in GABAergic interneurons." (PMID 37360784, 2023).
Left ventricular dilatation (1 paper, 2021). Enlargement of the chamber of the left heart ventricle. "Besides very clear signs of left ventricular dilatation and an increase in heart weight in ApoE−/−Fbn1C1039G+/− mice, also spleen and lung weight were significantly higher as compared to ApoE−/− mice." (PMID 35008828, 2021). "In addition, a marked reduction in left ventricular dilatation, cardiac fibrosis and heart weight was observed in ASA-treated ApoE−/−Fbn1C1039G+/− mice." (PMID 35008828, 2021).
Lewis lung carcinoma (1 paper, 2019). "However, in vivo studies using animal models that represent diseases with known MMP overexpression (e.g., tumor: Lewis lung carcinoma bearing mice; atherosclerotic plaques: apolipoprotein E-deficient mice) are needed to support their observation." (PMID 31426440, 2019). "However, preclinical PET/CT studies in disease models with known MMP up-regulation (e.g., tumor, Lewis lung carcinoma bearing mice; atherosclerotic plaques, apolipoprotein E-deficient mice) should be assessed." (PMID 31426440, 2019).
lipoma (1 paper, 2021). A benign, usually painless, well-circumscribed lipomatous tumor composed of adipose tissue. "Compared with ApoE−/− mice, ApoE plus DSCR-1 double null mutated mice 48 weeks old showed uneven hair surfaces and developed spontaneous keloid diathesis and lipomas." (PMID 33895138, 2021).
liver cirrhosis (1 paper, 2022). "Such approaches may be considered to treat late stages of NAFLD in progressive liver cirrhosis which are associated with major dysfunction of ApoE homeostasis in both the liver and the circulation." (PMID 36304458, 2022).
liver failure (1 paper, 2019). A liver disease characterized by the liver losing or has lost all of its function. "Achieving this goal is challenging for two reasons: first, the classical approach used to induce liver failure is to work with mice knockout for apolipoprotein E and lipoprotein receptors." (PMID 31130652, 2019).
metastasis (1 paper, 2018). The spread or migration of cancer cells from one part of the body (where they first appeared) to another. "We found that ApoE expression level proved rising tendency in stage II tumor, primary tumor and liver metastasis of CLM in order, and high ApoE expression was associated with shorter PFS in stage II cohort." (PMID 30631342, 2018).
motor neuron degeneration (1 paper, 2022). "Myelin oligodendrocyte glycoprotein (MOG), haptoglobin, apolipoprotein C-III (ApoC-III), and apolipoprotein E (ApoE), all failed to recapitulate the motor disability and motor neuron degeneration observed with sALS CSF and ApoB." (PMID 36043141, 2022).
mucositis (1 paper, 2012). Mucositis is inflammation and damage of the mucous membranes lining the mouth and other parts of the gastrointestinal (GI) tract. "Altogether, these findings suggest that the novel ApoE COG 133 mimetic peptide can reduce 5-FU-induced intestinal changes and potentially benefit mucositis." (PMID 22524518, 2012). "Regarding mediators that might be altered by ApoE mimetic peptides, TNF-α and IL-1β are important pro-inflammatory cytokines activated by NF-κB pathway, which is up-regulated during the pathogenesis of 5-FU-induced mucositis." (PMID 22524518, 2012).
muscle tumors (1 paper, 2023). "In addition, 25 DPs are related to muscle tumors; 8 DPs (APOE, FCER1A, FCER2, GSK3B, HSPD1, IL6R, MMP7, and RARRES2) are linked to proliferation of muscle cells." (PMID 36918772, 2023).
muscular dystrophy (1 paper, 2024). Muscular dystrophy (MD) refers to a group of more than 30 genetic diseases characterized by progressive weakness and degeneration of the skeletal muscles that control movement. "High CHOL or nonHDL-C caused by ApoE KO, rather than low HDL-C, likely lead to rodent muscular dystrophy phenotype humanization." (PMID 39138561, 2024).
Myelopathy (1 paper, 2020). Myelopathy is an descriptive term, referring to pathology leading to a neurologic deficit related to the spinal cord. "Interestingly, in the APOE gene ethnicity appears to result in conflicting genetic effects, with the ε2 allele associated with myelopathy in Indian populations and the ε4 allele associated with myelopathy in Chinese populations." (PMID 31968564, 2020).
Neovascular age related macular degeneration (1 paper, 2023). "A study that included 192 nvAMD (Neovascular age related macular degeneration) patients who received anti-VEGF treatment found that the APOE ε4 allele was significantly associated with significant visual improvement compared to APOE alleles at 3,6 and 12 month after treatment initiation." (PMID 37199411, 2023).
Nephroblastoma (1 paper, 2023). An embryonal neoplasm characterized by the presence of epithelial, mesenchymal, and blastema components. "At the same time, we observed downregulation of some pro-inflammatory factors: TNFRSF21, apolipoprotein E (APOE), nephroblastoma-overexpressed protein (NOV), and PDZ-binding protein (PBK)." (PMID 36829800, 2023).
nephrolithiasis (1 paper, 2019). The presence of a calculus in the pelvis of the kidney; this is most often composed of mineral salts and proteins. "The reduced expression of SIRT1 in the crystal group was both observed in the wild-type mice and the ApoE KO mice, revealing the potential role of SIRT1 in the nephrolithiasis." (PMID 30714469, 2019).
neuritis (1 paper, 2023). A neuropathy arising from inflammation of one or more nerves. "In vivo studies using ApoE/hAPPFAD ApoE4 resulted in a significant increase in the number of Aβ deposition and neuritis plaques in mice compared to ApoE3." (PMID 37333457, 2023).
neuropathic pain (1 paper, 2022). Chronic pain caused by damage to nerve fibers. "Synaptic proteins such as gelsolin, apolipoprotein C1, apolipoprotein E, contactin-1, and neural cell adhesion molecule L1-like protein were altered in cerebrospinal fluid of neuropathic pain patients and contributed to pain treatment." (PMID 36545122, 2022).
neurovascular disorder (1 paper, 2022). A disorder of the nervous system related to a vascular etiology. "Despite the protective effect of APOE ɛ2 against ADRD previously discussed, carrying an ɛ2 allele has been associated with elevated risks for cardio- and neurovascular disorders." (PMID 36512526, 2022).
nicotine dependence (1 paper, 2016). Physical and psychological dependence on nicotine. "The adverse effects on lifespan of the two associated loci have both likely been hidden from natural selection, CHRNA3/5 because its effect is mediated through the modern risk of nicotine dependence and APOE, because its effect occurs long after child-bearing age." (PMID 27029810, 2016).
nodular pulmonary amyloidosis (1 paper, 2019). "ApoE, ApoAI, ApoAIV, collagen, and vitronectin were also identified by mass spectrometry in a nodular pulmonary amyloidosis series published recently." (PMID 31531279, 2019).
non-Hodgkin lymphoma (1 paper, 2022). Distinct from Hodgkin lymphoma both morphologically and biologically, non-Hodgkin lymphoma (NHL) is characterized by the absence of Reed-Sternberg cells, can occur at any age, and usually presents as a localized or generalized lymphadenopathy associated with fever and weight loss. "Specifically, we observed the expression of APOE transcripts ENST00000252486, ENST00000425718, ENST00000434152, ENST00000446996, and ENST00000485628 to significantly differ between non-Hodgkin’s lymphoma and non-diseased B-cells." (PMID 36873459, 2022).
non-ischemic cardiomyopathy (1 paper, 2021). "However, it is not clear if apoE has a role in development of non-ischemic cardiomyopathy." (PMID 34816004, 2021).
oligodendroglioma (1 paper, 2021). A well-differentiated (WHO grade II), diffusely infiltrating neuroglial tumor, typically located in the cerebral hemispheres. "Finally, we observed a higher level of APOE, BMP4, KCNN3/SK3, and CRYAB proteins in astrocyte-like cells, whereas the IDH1 enzyme appears to be more expressed in oligodendrocyte-like cells in oligodendroglioma." (PMID 33925547, 2021).
osteomyelitis (1 paper, 2023). An acute or chronic inflammation of the bone and its structures due to infection with pyogenic bacteria. "ApoE deficiency mediates macrophage resistance to S. aureus osteomyelitis via regulation of cholesterol metabolism." (PMID 37529351, 2023). "Further transcriptome analyses and in vitro experiments evaluate how ApoE deficiency enhances cholesterol biosynthesis to inhibit cholesterol loss, mediating macrophage resistance to S. aureus osteomyelitis." (PMID 37529351, 2023). "Mechanically, ApoE deficiency potentiates macrophage resistance to S. aureus osteomyelitis via regulating cholesterol metabolism." (PMID 37529351, 2023). "Although we found that ApoE deficiency could improve macrophage bacterial clearance in S. aureus osteomyelitis, there are some limitations in our study." (PMID 37529351, 2023). "Our study reveals the role of ApoE in S. aureus osteomyelitis, suggesting that reprogramming of cholesterol metabolism is an essential host defense strategy against S. aureus osteomyelitis." (PMID 37529351, 2023). "We identified a previously unrecognized role of ApoE in S. aureus osteomyelitis from the perspective of metabolic reprogramming." (PMID 37529351, 2023). "To explore how ApoE functions in the regulation of cholesterol metabolism during S. aureus osteomyelitis, we performed transcriptome analysis of the WT and Apoe-/- femur bone marrow using high-throughput sequencing." (PMID 37529351, 2023). "In this study, we conducted in vitro and in vivo experiments to define the effects of S. aureus osteomyelitis on cholesterol metabolism, as well as the role of Apolipoprotein E (ApoE) in regulating cholesterol metabolism by macrophages during S. aureus osteomyelitis." (PMID 37529351, 2023). "Based on these studies, it is worth investigating the role of ApoE in S. aureus osteomyelitis." (PMID 37529351, 2023). "However, we cannot exclude the possibility that ApoE may affect the pathogenesis of S. aureus osteomyelitis through other mechanisms." (PMID 37529351, 2023).
osteophytes (1 paper, 2020). "In addition, ApoE*3Leiden.CETP males showed high scores for both osteophyte formation and synovitis, while females developed almost no osteophytes but demonstrated high synovitis scores and significantly higher plasma cholesterol levels." (PMID 32456298, 2020).
ovarian tumors (1 paper, 2025). "Indeed, ApoE was found to be expressed on stromal fibroblasts on the borders of ovarian tumors, and these cells ordinarily interact with LRP5 receptors on the tumor cell surface, posing another mechanism that allows ApoE to induce proliferation of the cancer cells." (PMID 40149482, 2025).
overnutrition (1 paper, 2023). An imbalanced nutritional status resulting from excessive intake of nutrients. "Future in vivo studies may investigate overexpression ApoE to confirm its anti-inflammatory effects in overnutrition." (PMID 38062308, 2023). "Here, the elevation of plasma LPS levels in HFD-fed mice and the reduction in ApoE expression following LPS stimulation indicate that ApoE may regulate metabolism and inflammation induced by overnutrition." (PMID 38062308, 2023).
papilloma (1 paper, 2024). A benign epithelial neoplasm that projects above the surrounding epithelial surface and consists of villous or arborescent outgrowths of fibrovascular stroma. "Most SKH-hr2+ApoE mice developed SCCs, some originating from multiple papillomas that grew and merged into large, rough masses." (PMID 39456640, 2024). "This is especially true for the Skh-hr2+ApoE model, where the formation of papillomas occurs in significant numbers and relatively early." (PMID 39456640, 2024). "The SKH-hr2+ApoE model presented with small wounds by the fourth month, and the emergence of the first papillomas was noted by the fifth month." (PMID 39456640, 2024). "Compared to the other three models, the SKH-hr2+ApoE model exhibited a higher papilloma count, with the SKH-hr1 model developing the fewest." (PMID 39456640, 2024). "The SKH-hr2+ApoE model developed its initial papillomas in the third month, the Nude model in the fourth month, and both the SKH-hr1 and SKH-hr2 models in the fifth month." (PMID 39456640, 2024). "The SKH-hr2+ApoE model exhibited the highest mean number of papillomas (M = 3.233, 95% CI [2.3882, 4.078]), significantly greater than the other models, followed by the SKH-hr2 (M = 1.042) and Nude (M = 0.698) models, with the SKH-hr1 model showing the lowest mean (M = 0.175)." (PMID 39456640, 2024). "The earlier onset of papillomas and cancer in the SKH-hr2+ApoE models, followed by the later appearance but rapid growth of cSCC in the SKH-hr2 models, underscores a complex interplay between genetic predispositions and the carcinogenic process." (PMID 39456640, 2024).
Paralysis (1 paper, 2019). Paralysis of voluntary muscles means loss of contraction due to interruption of one or more motor pathways from the brain to the muscle fibers. "This resulted in a 12-feature prediction model consisting of six serum proteins (AACT, APOE, APOH, FETUA, HBA and PHLD), three sociodemographic factors (body mass index, childhood trauma and education level) and three depressive symptoms (sadness, fatigue and leaden paralysis)." (PMID 31699963, 2019).